CTNNB1 (catenin beta 1)
Diseases named in the same sentence as CTNNB1 in open-access papers (continued):
Sharing a sentence is not in itself a finding about the gene and the disease.
basal cell adenocarcinoma (2 papers, 2021 to 2023). "Another study found CTNNB1 mutations in basal cell adenomas and, among other alterations, focal CYLD deletion and biallelic inactivation of NFKBIA in a case of basal cell adenocarcinoma." (PMID 32892208, 2021).
benign liver neoplasm (2 papers, 2022 to 2025). "Being a benign liver neoplasm with risk of malignant transformation, HCA has more than 10% frequency of CTNNB1 mutation." (PMID 36122209, 2022).
biliary tract cancer (2 papers, 2020 to 2024). "DKK1 expression together with CTNNB1 was found to worsen overall survival, as well as relapse-free survival, even in the presence of CD8+ tumor-infiltrating lymphocytes in biliary tract cancer." (PMID 39513892, 2024).
bone tumor (2 papers, 2022 to 2023). "We show osteoma to represent the first bone tumor associated with the relatively “simple” and recurrent genetic background of single nucleotide variants in the CTNNB1 gene and thus provide evidence for a genetically defined, true neoplasm." (PMID 34725446, 2022).
breast invasive carcinomas (2 papers, 2016 to 2018). "In addition, analysis of a dataset of 887 patients with invasive breast carcinoma showed that coreduction of CTNNB1 (Wnt) and YAP1 (YAP) protein expression was correlated with improved patients’ survival (median survival of 140.18 months versus 74.67 months in the unaltered control)." (PMID 29316250, 2018). "The collective % of alterations in CTNNB1, APC and DVL1 genes among total breast invasive carcinomas were 21% in contrast to 56% breast invasive carcinomas, PAM50 Basal-like." (PMID 27281609, 2016).
carcinosarcoma (2 papers, 2020). A malignant tumor composed of a mixture of carcinomatous and sarcomatous elements. "Previous studies demonstrate that CTNNB1 mutation and subsequent activation of the Wnt signaling pathway play an important role in tumorigenesis of L-FLAC and PB tumors, but not in carcinosarcoma." (PMID 32209061, 2020).
Chronic Myeloid Leukemia (2 papers, 2013 to 2018). "In this study, when we look at doxorubicin-resistant K562 chronic myeloid leukemia cells, there was no significant change in expression of CTNNB1 gene encoding beta-catenin; as well as an increase of about 8-folds was observed in the gene encoding FZD1 from Wnt receptors." (PMID 29805346, 2018).
co-infection (2 papers, 2025). "Subsequently, we obtained the top 16 hub targets of probenecid for SARS-CoV-2/RSV co-infection, namely, AKT1, ALB, EGFR, CASP3, CTNNB1, SRC, HSP90AA1, and so on." (PMID 40371107, 2025).
colon adenoma (2 papers, 2015 to 2016). An adenoma that arises from the colon. "First, APC or CTNNB1 mutations in LGR5+ colon stem cells give rise to human colon adenomas by constitutively activating WNT signaling to sustain the intestinal SC program and bypass cellular differentiation." (PMID 26744320, 2016). "While it is known that APC or CTNNB1 mutation activates aberrant WNT signaling to give rise to colon adenomas, the programs that promote their transformation to carcinomas are not well characterized." (PMID 26744320, 2016).
dyslipidemia (2 papers, 2016 to 2019). "On the contrary, group B had a metabolic syndrome, CTNNB1 mutation, and an inflammatory response." (PMID 31696344, 2019).
dysplasia (2 papers, 2021 to 2022). A usually neoplastic transformation of the cell, associated with altered architectural tissue patterns. "Sporadic FGPs without dysplasia have mutations in the gene encoding β-ceratin (CTNNB1) but lack APC alterations, whereas sporadic FGPs with low-grade dysplasia display APC alterations but usually lack germline mutations in the CTNNB1 gene." (PMID 36553595, 2022).
epilepsy (2 papers, 2019 to 2025). A brain disorder characterized by episodes of abnormally increased neuronal discharge resulting in transient episodes of sensory or motor neurological dysfunction, or psychic dysfunction. "Specifically, we will describe most common CTNNB1 syndrome symptoms with a focus on its association with epilepsy." (PMID 39949392, 2025). "Further research is needed to elucidate the specific molecular interactions affected by CTNNB1 mutations, which could lead to more targeted and effective treatments for epilepsy in this patient group." (PMID 39949392, 2025). "CTNNB1 has been implicated in epilepsy because of its altered postseizure expression." (PMID 31214268, 2019). "The exact mechanisms by which CTNNB1 mutations cause epilepsy remain unclear." (PMID 39949392, 2025). "Yet, the possibility of epilepsy was not immediately considered, partly due to my inexperience as a new parent unaware of what signs to look for, and partly because there weren't enough known cases of CTNNB1 linked to epilepsy at that time." (PMID 39949392, 2025).
fibrolamellar carcinoma (2 papers, 2012 to 2022).
Follicular Thyroid Carcinoma (2 papers, 2015 to 2021). "A similar result for the CTNNB1 gene expression was obtained when low-differentiated follicular thyroid cancer cells (FTC-133 cell line) were exposed for 4 h or 3 days to the RPM." (PMID 34277614, 2021).
hereditary nonpolyposis colorectal carcinoma (2 papers, 2014 to 2021). "CTNNB1 mutations are found in 5% of human CRC with and without corresponding mutations in APC especially in hereditary nonpolyposis colorectal cancer (HNPCC) patients where the frequency of CTNNB1 mutation rises." (PMID 25162504, 2014).
human papilloma virus infection (2 papers, 2016 to 2020). An infectious process caused by a human papillomavirus.
hyperekplexia (2 papers, 2016 to 2017). "Recently, a clear correlation of mutation in β-catenin gene (CTNNB1) with an atypical syndromic hyperekplexia had been reported in a case of CTNNB1-related syndrome and CTNNB1 was considered to be a cause gene for syndromic hyperekplexia." (PMID 28985719, 2017). "We for the first time associate CTNNB1 mutation with hyperekplexia identifying it as an additional candidate for consideration in patients with startle syndrome." (PMID 26968164, 2016). "CTNNB1 should be considered a candidate in patients with hyperekplexia in whom classical genetic mechanisms identified to date are negative." (PMID 26968164, 2016). "Our patient expresses hyperekplexia, a unique symptom that has not been seen among other reported CTNNB1 patients." (PMID 26968164, 2016).
hyperplasia (2 papers, 2021 to 2023). An abnormal increase in the number of cells in an organ or a tissue with consequent enlargement. "Since CTNNB1 mutations seemingly occur in atypical endometrial hyperplasia, CTTNB1 mutation plays a critical role in the initiation and early progression of EEC tumors." (PMID 33450701, 2021).
inflammatory myofibroblastic tumor (2 papers, 2011 to 2022). A multinodular intermediate fibroblastic neoplasm that arises from soft tissue or viscera, in children and young adults. "Powerful prognostic data also is emerging such as in inflammatory myofibroblastic tumor with ALK rearrangements and possibly CTNNB1 mutations in desmoids." (PMID 21403834, 2011).
influenza pneumonia (2 papers, 2021 to 2022). "For example, CTNNB1 activation enhanced the inflammatory activity of alveolar macrophages and facilitated acute host morbidity in a murine influenza pneumonia model." (PMID 36387401, 2022). "CTNNB1 abnormal expression is often closely related to the development of tumors, for its role in pneumonia is also thought to be immune homeostasis or not the citizenry." (PMID 34803705, 2021). "Results suggested that 5 proteins with greater node degrees [i.e. catenin beta-1 (CTNNB1), integrin beta-1 (ITGB1), catenin alpha-1 (CTNNA1), dynamin-2 (DNM2), Keratin, type I cytoskeletal 19 (KRT19)] might function as crucial players in pneumonia-related bacterial infection in FMD." (PMID 36387401, 2022).
intrahepatic cholangiocarcinoma (2 papers, 2024 to 2026). A carcinoma that arises from the intrahepatic bile duct epithelium in any site of the intrahepatic biliary tree.
invasive carcinoma (2 papers, 2016 to 2023). A carcinoma that is not confined to the epithelium, and has spread to the surrounding stroma. "Using cBioPortal, here we found that collective % of alteration(s) in WP genes, CTNNB1, APC and DVL1 among breast-invasive-carcinomas was 21% as compared to 56% in PAM50 Basal." (PMID 27281609, 2016).
ischemia (2 papers, 2019 to 2025). A hypoperfusion of the BLOOD through an organ or tissue caused by a PATHOLOGIC CONSTRICTION or obstruction of its BLOOD VESSELS, or an absence of BLOOD CIRCULATION. "Together with the also observed ischemia-derived reduction of β-catenin 1 (Ctnnb1), which is interacting with N-cadherin, these changes might critically affect cell-cell adhesion processes." (PMID 31089963, 2019).
ischemic stroke (2 papers, 2025). A stroke disorder caused by obstruction of blood flow to the brain, due to thrombotic (local blood clot formation) or embolic (due to a blood clot or other material traveling from another site) event. "Some studies have found that CTNNB1 can be a potential drug target for the treatment of ischemic stroke." (PMID 40786625, 2025). "Twelve genes have been reported as potential regulators of HT in ischemic stroke in previous studies: Casp3, Csf2, Ctnnb1, Cxcl12, Hif1a, Il1b, Mtor, Ptgs2, Ptprc, Tlr2, Tlr4, and Vcam1." (PMID 40002863, 2025).
liver fibrosis (2 papers, 2022 to 2023). "Since the genes of Smad4, Jun, Ctnnb1, and Smad5 have been reported to be associated with liver fibrosis, and the Notch2 gene was considered to be related to Wnt and TGF-β signaling pathways, these five candidate target genes were selected for research." (PMID 35883205, 2022).
lymphoma (2 papers, 2022 to 2024). A malignant (clonal) proliferation of B- lymphocytes or T- lymphocytes which involves the lymph nodes, bone marrow and/or extranodal sites. "Our findings support this proposed mechanism with CTNNB1 being upregulated in lymphoma (log2FC = 1.1, FDR = 1.54 × 10−33), while other elements of the CTNNB1 “destruction complex” were mostly downregulated." (PMID 36873459, 2022).
metastatic colorectal cancer (2 papers, 2014 to 2025). "In metastatic colorectal cancer, this heterogeneity can be detected through the distinct expression patterns of caudal type homeobox 1 (CDX1), CDX2, and/or catenin beta 1 (CTNNB1)." (PMID 40565003, 2025).
mucosal (2 papers, 2017 to 2019). "CTNNB1 is a component of the cadherin cell-cell adhesion complex in epithelia, and its function may be particularly important in the context of mucositis, which involves the breakdown of the mucosa." (PMID 28678827, 2017).
mucosal melanoma (2 papers, 2019 to 2021). A melanoma that arises from a mucosal site. "CTNNB1, coding for β-catenin, was found mutated in 15% of ConjMel cases, while they were exceptional in CM and mucosal melanomas (~5%)." (PMID 34359736, 2021).
odontogenic cyst (2 papers, 2022 to 2025). A cyst in the jaw that arises from tissues of tooth development. "Other potentially relevant events, such as DNA replication errors, have been discussed in odontogenic cysts and tumors which are also mainly benign despite harboring activating MAP Kinase or CTNNB1 mutations." (PMID 36077603, 2022). "Indeed, aberrations in the MAPK, Sonic Hedgehog (SHH), and WNT/β-catenin pathways are well documented in odontogenic cysts and tumors, with BRAF, PTCH1, and CTNNB1 representing the most frequently altered genes." (PMID 41364259, 2025).
oral mucositis (2 papers, 2016 to 2019). Inflammation of the mucous membranes of any of the structures in the mouth. "In conclusion, we found that CTNNB1 rs1880481, CTNNB1 rs3864004, and GSK3B rs375557 were correlative with the curative efficacy of RT, and that GSK3β rs375557 and APC rs454886 were correlative with acute grade 3–4 radiation-induced dermatitis and oral mucositis." (PMID 27769064, 2016).
Pancreatic cysts (2 papers, 2023 to 2024). A cyst of the pancreas that possess a lining of mucous epithelium. "This approach allows for the identification of various pancreatic cyst types, including serous cystadenomas, solid-pseudopapillary neoplasms, and cystic neuroendocrine tumors, which are characterized by specific mutations in the VHL, CTNNB1, and MEN1 genes, respectively." (PMID 38539568, 2024).
Parkinson disease (2 papers, 2013 to 2023). A progressive degenerative disorder of the central nervous system characterized by loss of dopamine producing neurons in the substantia nigra and the presence of Lewy bodies in the substantia nigra and locus coeruleus. "Furthermore, this study shed light on the altered gene expression of CTNNB1, NDUFS6, and CAV1 in PBMC, which could serve as biomarkers for detecting pesticide-related Parkinson’s disease." (PMID 37508933, 2023).
pulmonary blastoma (2 papers, 2014 to 2022). A malignant neoplasm of the lung composed of tubular structures and immature mesenchymal elements, which may differentiate towards skeletal and smooth muscle, cartilage or a combination of muscle and cartilage.
sarcopenia (2 papers, 2023 to 2024). Progressive decline in muscle mass due to aging which results in decreased functional capacity of muscles. "Prostaglandin signaling pathways are closely related to inflammation, but also muscle regeneration and processes associated with frailty and sarcopenia, whereas β-catenin (CTNNB1 gene) as a part of Wnt signaling is also involved in the differentiation of muscle cells and fibrosis." (PMID 37629065, 2023). "Notably, CTSS and CTNNB1 were found to be central in the network, suggesting a potential key role in the pathophysiology of sarcopenia." (PMID 38644354, 2024). "Patients with sarcopenia were characterized by the highest expression of PTGER4 and CTNNB1 in whole blood samples." (PMID 37629065, 2023). "The highest median of the CTNNB1 mRNA level was observed in patients with sarcopenia, but it was not statistically significant compared with the geriatric control and patients with frailty syndrome." (PMID 37629065, 2023).
small cell lung carcinoma (2 papers, 2017 to 2023). Small cell lung cancer (SCLC) is a highly aggressive malignant neoplasm, accounting for 10-15% of lung cancer cases, characterized byrapid growth, and early metastasis. "In small-cell lung cancer (SCLC), the mutation in APC and CHD8, which inhibits transcription mediated by CTNNB1, is related to the relapse of SCLC." (PMID 37190019, 2023). "CTNNB1 and CDH1 were expressed in 90% (54/60) of small cell lung cancer cells, in which weak expression (score between 10 and 20) was 11.11%, moderate (score between 20 and 100) was 70.37% and strong (score between 100 and 300) was 18.52%." (PMID 29115924, 2017).
thymoma (2 papers, 2024 to 2025). A neoplasm arising from the epithelial cells of the thymus. "By the ssGSEA method, we proved that CTNNB1, EGFR, SOX2, and ERBB2 expressions showed significant correlation with Th17 T cell in thymoma, and KEGG analysis suggested that differential genes were highly enriched in the IL-17 pathway." (PMID 39192657, 2025). "CTNNB1, EGFR, SOX2, and ERBB2 expressions revealed a significant correlation with NK cells in thymoma, and these four genes may play a role in regulating NK cells in TAMG." (PMID 39192657, 2025).
thyroid (2 papers, 2022 to 2025). "Molecular alterations in the Wnt/β-catenin signaling pathway involved in adenomatous polyposis coli (APC), axis inhibition protein 1 (AXIN1), and catenin beta 1 (CTNNB1) contribute to thyroid tumorigenesis." (PMID 36157447, 2022).
uterine corpus endometrial carcinoma (2 papers, 2019 to 2020). A endometrial carcinoma (disease) that involves the body of uterus. "In uterine corpus endometrial carcinoma (UCEC), catenin beta 1 (CTNNB1) mutation showed an association with low-SST2 status." (PMID 32335823, 2020).
uterine fibroids (2 papers, 2020 to 2022). "We observed multiple deregulated signaling pathways, including those for IGF-1, neuregulin, mTOR, TGFB1, CTNNB1, and TNF, in the mouse uterine leiomyomas." (PMID 33244099, 2020).
Vitreoretinopathy (2 papers, 2021 to 2022). Ocular abnormality characterized by premature degeneration of the vitreous and the retina that may be associated with increased risk of retinal detachment. "Recent studies also associated missense or truncating variants of CTNNB1 with vitreoretinopathy and suggested that ophthalmologic examination should be performed in every patient with CTNNB1-related disorders." (PMID 35935366, 2022). "All patients but one presented with a spectrum of ocular abnormalities and one patient, who was found to carry a missense variant in CTNNB1, had notable vitreoretinopathy." (PMID 33350591, 2021). "There are now multiple cases of CTNNB1‐related neurodevelopmental disorder or NEDSDV and some kind of vitreoretinopathy in the literature." (PMID 33350591, 2021).
achondroplasia (1 paper, 2025). Achondroplasia is the most common form of chondrodysplasia, characterized by rhizomelia, exaggerated lumbar lordosis, brachydactyly, and macrocephaly with frontal bossing and midface hypoplasia. "A recent analysis has raised the possibility that LoF variants in CTNNB1 lead to a selective advantage in the male germline, as observed in achondroplasia." (PMID 40684264, 2025).
acute lymphoblastic leukemia (1 paper, 2023). Leukemia with an acute onset, characterized by the presence of lymphoblasts in the bone marrow and the peripheral blood. "We have now investigated the role of β‐catenin/CTNNB1 in the evolution of T‐cell Acute Lymphoblastic Leukemia (T‐ALL) patients and its involvement in therapy resistance." (PMID 36597789, 2023).
aldosteronomas (1 paper, 2022). "As found in other adrenocortical tumors, somatic gain of function variants in CTNNB1 gene, encoding β catenin, also have been reported in around 5% of aldosteronomas." (PMID 35813615, 2022). "Aldosteronomas are a major cause of unilateral PA, associated with somatic variants in KCNJ5, CACNA1D, ATP1A1, ATP2B3, CLCN2, CACNA1H and CTNNB1 genes." (PMID 35813615, 2022).
alveolar rhabdomyosarcoma (1 paper, 2018). A rapidly growing malignant mesenchymal neoplasm. "The two main subtypes are alveolar rhabdomyosarcoma (ARMS), which is associated with PAX3/7-FOXO1 fusion genes, and embryonal rhabdomyosarcoma (ERMS), which is associated with mutations in common cancer genes such as HRAS, KRAS, NRAS, CTNNB1, PIK3CA and TP531." (PMID 30353028, 2018).
ameloblastic carcinoma (1 paper, 2021). A rare, cytologically malignant ameloblastoma that may metastasize.
anaplastic gliomas (1 paper, 2025). "Our results on the CTNNB1 gene (β-catenin) showed that mutations were specifically frequent in anaplastic gliomas." (PMID 40679044, 2025).